TMEM44-AS1 (TMEM44 antisense RNA 1)
Gene: Long non-coding RNA gene on chromosome 3 (194,583,969 to 194,590,263, forward strand). Ensembl gene ENSG00000231770.
Diseases named in the same sentence as TMEM44-AS1 in open-access papers:
TMEM44-AS1 is named in the same sentence as 2 diseases in open-access papers, as found by Europe PMC text mining. Sharing a sentence is not in itself a finding about the gene and the disease. The quoted sentences say what the papers report.
glioma (2 papers, 2021 to 2024). A benign or malignant brain and spinal cord tumor that arises from glial cells (astrocytes, oligodendrocytes, ependymal cells). "To address the translational potential of TMEM44-AS1, we prioritized Small-Molecule Myc inhibitors, Myci975, for further investigation based upon the positive feedback loop of TMEM44-AS1/ Myc in glioma." (PMID 34696771, 2021). "To address the translational potential of TMEM44-AS1/Myc, we identified the Myc inhibitor, Myci975, as a selective inhibitor of glioma cell growth, which further validates our finding that Myc is a downstream effector of TMEM44-AS1." (PMID 34696771, 2021). "And interestingly, we found that TMEM44-AS1 is coincidently a mediator for p38MAPK signaling in glioma cells." (PMID 34696771, 2021). "Additionally, Myc protein expression was generally reduced in the TMEM44-AS1 knockdown LN-18 and U251 glioma cells, whereas increased in TMEM44-AS1-overexpression SF126 glioma cells." (PMID 34696771, 2021). "Interestingly, we found that TMEM44-AS1 expression was decreased by Myc knockdown in LN-18 and U251 glioma cells, and overexpression of Myc increased TMEM44-AS1 expression in SF126 glioma cells." (PMID 34696771, 2021). "TMEM44-AS1 induces proliferation, migration, and invasion in LN-18 and U251 glioma cells via the TMEM44-AS1/Serpin B3/c-Myc and TMEM44-AS1/Serpin B3/EGR1/IL-6 signaling pathways." (PMID 38786726, 2024). "Analysis of the subcellular distribution of TMEM44-AS1 by RT-qPCR analysis indicates that TMEM44-AS1 presence in the cytoplasm and nucleus of LN-18 and U251 glioma cells." (PMID 34696771, 2021).
tumor (2 papers, 2021 to 2023). "We confirmed that TMEM44-AS1 knockdown inhibited the TMEM44-AS1 expression in xenografted tumor tissues." (PMID 34696771, 2021). "This suggests that knockdown of TMEM44-AS1 blocked the cycle of tumor cells." (PMID 38040698, 2023). "And knockdown of TMEM44-AS1 tumor weight is lower than those in the sh-con group." (PMID 34696771, 2021).